KRAS (KRas proto-oncogene, GTPase)
Diseases named in the same sentence as KRAS in open-access papers (continued):
Sharing a sentence is not in itself a finding about the gene and the disease.
pancreatic cancer (continued). "In KRAS‐mutant pancreatic cancer cohort (n = 133), a strong correlation between PLK1 and FGF9, FGF14 was observed, and in KRAS‐mutant colon cancer (n = 170), only FGF14 strongly correlated with PLK1." (PMID 34369083, 2021). "When a KRAS siRNA was intravenously delivered by this tumor-penetrating nanocomplex into a genetically engineered PDAC mouse model, the growth of pancreatic tumors arising from allografted KP D8-175 cells were significantly delayed." (PMID 34683931, 2021). "Importantly, our SWI/SNF-altered pancreatic cancer group not receiving immunotherapy similarly did not have a KRAS mutation in 2 of 5 (40%) patients with available data, underscoring the likely genomic relevance of SWI/SNF complex members in pancreatic cancer carcinogenesis." (PMID 34375311, 2021). "Here the authors show that KRAS Q61H is decoupled from SHP2- mediated upstream regulation, thus Q61H pancreatic cancer cells maintain MAPK signalling and are refractory to SHP2 inhibitors." (PMID 34725361, 2021). "Given the co-occurrence of mutant KRAS with high HIF-1α and high galectin-3 levels in pancreatic cancer, our results suggest an application of Hsp90 inhibitors in this cancer type." (PMID 33672199, 2021). "This is also in line with the recent finding that in pancreatic cancer cells and PDAC cells in particular, mutant KRAS‐driven transcriptional reprogramming results in enhanced macropinocytosis to meet the high tumor metabolic needs." (PMID 37366462, 2021). "We used KRAS-driven murine PAN 02 and human L3.6pl pancreatic cancer cells to test the effectiveness of DFMO and GW5074 treatments at previously optimized concentrations, alone and in combination, to inhibit pancreatic tumor cell growth." (PMID 34947972, 2021). "KRAS activates the expression of the Vacuole Membrane Protein 1 (VMP1) to induce and maintain autophagy levels in pancreatic tumor cells." (PMID 32655498, 2020). "Using siRNA-mediated knockdown of PRDM3 in PK-8 pancreatic cancer cells, Tanaka and colleagues also showed that PRDM3 promotes pancreatic cancer cell proliferation and migration through the inhibition of a KRAS suppressor miR-9614." (PMID 32179733, 2020). "In this study, we use Met-directed immunoPET and RLT in models of human pancreatic cancer that are resistant to Met- and MEK-selective TKIs, despite over-expression of Met and KRAS-pathway activation." (PMID 31903112, 2020). "MiR-126 is also the target of other important oncogenes such as KRAS and CRK in pancreatic cancer Therefore, overexpression of miR-126 in SPNs-treated cells can be a reason for inhibition of MIA PaCa-2 proliferation and migration." (PMID 32489562, 2020). "Interestingly, the transcriptional and metabolic changes induced by the stromal secretome overlapped with those induced by oncogenic KRAS, indicating that the stromal reaction might cooperate with oncogenic alterations in KRAS to drive pancreatic cancer progression." (PMID 32752017, 2020). "In pancreatic cancer, both the activation of YAP by mutant KRAS and the redundancy of YAP and mutant KRAS pathways have been discovered in a KRAS-driven mouse neoplasia model." (PMID 32545208, 2020).
pancreatic cancer (continued). "In a previous work, we have identified VMP1 as a transcriptional target of oncogenic KRAS signaling pathway and demonstrated that KRAS requires VMP1 to induce and maintain basal autophagy in pancreatic tumor cells." (PMID 32655498, 2020). "Besides, recent research demonstrated that exosomes could directly and specifically target the oncogenic KRAS, which is also an essential gene in the development of pancreatic cancer, this made exosomes to be the best novel therapeutic candidates for pancreatic cancer." (PMID 32854710, 2020). "Both KRAS and EGFR are essential mediators of pancreatic cancer development and interact with Argonaute 2 (AGO2) to perturb its function." (PMID 32499547, 2020). "As a ubiquitously expressed transcription factor, MAZ binds to GC‐rich cis‐elements through its C2H2‐type ZNF motif and activates transcription of KRAS and vascular endothelial growth factor (VEGF) in pancreatic cancer, cervical cancer, and glioblastoma cells." (PMID 31709724, 2019). "In summary, the studies reported here illustrate the role of DCLK1 in KRAS activation, PDAC tumor cell invasion, drug resistance, pancreatic tumor growth in vivo, and overall patient survival." (PMID 31467540, 2019). "We next expressed Tet-inducible shRNA against human LIF in multiple human pancreatic cancer cell lines, to study the role(s) LIF plays in KRAS-driven pancreatic cancer maintenance." (PMID 31296870, 2019). "In a previous study, we detected multiple pancreatic cancer cell lines and confirmed that PANC‐1 cells (KRASG12D) had the highest expression level of the KRAS oncoprotein." (PMID 30347501, 2019). "Targeting SHP2 further sensitized pancreatic cancer cells to MEK inhibition and promoted a senescence response in KRAS-mutant non-small cell lung cancer models under nutrient-restricted conditions." (PMID 31681559, 2019). "But growing evidence has shown that cancer cells manage to survive the ablation of mutant KRAS by re-activation of compensatory pathways, such as YAP and AKT in KRAS-dependent pancreatic cancer mouse models." (PMID 30833665, 2019). "Consistently, in pancreatic cancer cells KRAS has been shown to increase GLI1 activity via MEK1/2-ERK1/2, and KRAS-mediated activation of GLI1 is suppressed with UO126, through decrease of GLI1 protein stability." (PMID 30934935, 2019). "In this regard, we present data showing KRAS regulates expression of LIF in mouse and human pancreatic cancers." (PMID 31296870, 2019). "To test the ability of an anti-KRAS NP to inhibit tumor growth, we inoculated mice subcutaneously with KPC-1 pancreatic cancer cells (2x105 cells per tumor injection)." (PMID 31413817, 2019). "Therefore, RON, an important KRAS effector, may play a very important role in pancreatic cancer." (PMID 31867280, 2019). "Inhibition of the interaction between PDE-delta and KRAS disrupted RAS localization and signaling and impaired cell proliferation in pancreatic cancer models." (PMID 31681559, 2019). "Recently, PL + GEM was shown to induce apoptosis and inhibit BxPC-3 (KRAS wildtype, BRAF mutant) pancreatic tumor growth in a subcutaneous model." (PMID 29535819, 2018). "Similarly, combined dabrafenib and trametinib resulted in growth-inhibitory synergism in 5/6 pancreatic cancer cell lines (all carrying a KRAS mutation, with the exception of T3 M4 and the non-neoplastic cell line HPDE) and frank antagonism in the KRAS-mut PANC1 cell line." (PMID 29986755, 2018). "From a mechanistic perspective, the present finding, together with our recent report that ILK controls the expression of oncogenic KRAS through a regulatory loop, underscores the pivotal role of ILK in promoting pancreatic cancer progression." (PMID 28692035, 2017).
pancreatic cancer (continued). "In the patients with wildtype KRAS, two ABTC patients achieved a PR, and four ABTC patients and one pancreatic cancer patient achieved SD." (PMID 27853997, 2017). "EGFR signaling is required for oncogenic KRAS-induced pancreatic tumorigenesis, and EGFR signaling activation also induces upregulation of FASN in pancreatic cancer cells in an ERK-dependent manner." (PMID 29295482, 2017). "Another group used digital PCR to detect alterations in KRAS, BRAF, and PIK3CA in pancreatic cancer patients, demonstrating that detection of any of these genes was associated with lower progression-free survival." (PMID 29137355, 2017). "MERTK is down‐regulated in KRAS‐mutant CRC and up‐regulated in pancreatic cancer cell lines resistant towards selumetinib." (PMID 29101300, 2017). "Stable transfection of the Gdeg reporter into two human pancreatic cancer cell lines with different oncogenic potentials of metastasis; KLM1 as high-ability cells with mutant KRAS, and BxPC3 as low-ability cells with wild-type KRAS." (PMID 26764906, 2016). "Here, we investigated whether deep sequencing of KRAS codons 12, 13 and 61 in cfDNA from plasma samples from a large series of more than 400 pancreatic cancer cases and 500 controls could represent a comprehensive assay for sensitive and specific detection of pancreatic cancer." (PMID 27705932, 2016). "Moreover, some pancreatic cancers harbor activating mutations of BRAF rather than KRAS." (PMID 25699241, 2015). "Thus, KRAS and BRAF oncogenes may function in a mutually exclusive manner in the transformation and carcinogenesis of pancreatic cancers; indeed, some studies suggest that a mutation in one of these two genes invariably results in retention of wild-type copies of the other." (PMID 24624093, 2014). "We now demonstrate that binding of RAGE to oncogenic KRAS facilitates hypoxia-inducible factor 1 (HIF1)α activation and promotes pancreatic tumor growth under hypoxic conditions." (PMID 25341034, 2014). "In pancreatic cancer, CDK5 is intrinsic to KRAS signaling through the centrally important RAL signal transduction pathway, thus providing a potential ‘druggable’ target for mutant KRAS tumors." (PMID 24841903, 2014). "Furthermore, aberrant expression of Notch induced by MMP-7 and ADMA metalloproteinase conjunct with KRAS mutation can prompt rapid reprogramming of acinar-to-ductal metaplasia (ADM), which has been hypothesized to play cardinal role in the evolvement of pancreatic cancer." (PMID 24587996, 2014). "Here, we observed downregulation of c-MYC and KRAS via let-7a in AsPC1 tumor xenografts following the knockdown of DCLK1 (a similar mechanism was previously demonstrated in pancreatic cancer cells)." (PMID 24040120, 2013). "To directly assess the role of K-Ras in CXCL12 signaling, we knocked down KRAS using siRNA and then exposed pancreatic cancer cell lines to CXCL12." (PMID 22472349, 2012). "The experiments were repeated in the pancreatic cancer cell lines Colo357 & PSN-1(both high Cten expressors and mutant for KRAS)." (PMID 21698197, 2011). "EGFR pathway genes, including, EGFR, KRAS, BRAF, and PIK3CA genes, are well-investigated oncogenes in many tumors including lung, colorectal (CRC), and pancreatic cancers (PAC)." (PMID 19826477, 2009). "Consistently, other studies showed that inhibition of NAMPT1 expression attenuated pancreatic cancer growth in vivo, and that NAD + kinase could be phosphoryl-activated by KRAS/PKC axis to support pancreatic cancer growth." (PMID 41391757, 2025).
pancreatic cancer (continued). "This builds on our earlier work showing RASON’s role in stabilizing KRASG12D and KRASG12V in pancreatic cancer and further suggests that RASON may be a universal regulator of mutant KRAS isoforms across cancer types." (PMID 40128846, 2025). "In some instances, concurrent deactivation of KRAS G12D and ICMT may accelerate disease progression in embryonic pancreatic cancer models." (PMID 40335986, 2025). "An essential modulator of the KRAS pathway, RALGDS (RAS-specific guanine nucleotide exchange factor) has drawn interest as a possible zone for the fabrication of novel molecules to treat pancreatic cancer." (PMID 40157967, 2025). "The preliminary results of a phase 1 trial evaluating a first-in-class, KRAS-G12D-selective protein degrader, ASP3082, in advanced pancreatic cancer, CRC, and NSCLC showed an acceptable safety profile and promising antitumor activity, especially in pretreated pancreatic cancer." (PMID 40361439, 2025). "A KRAS RNA G4 ligand 15a demonstrated its ability to effectively inhibit KRAS protein expression in pancreatic cancer cells (MIA PaCa-2 and PANC-1) without altering the mRNA levels, suggesting that 15a acts as a KRAS translational suppressor." (PMID 40333779, 2025). "This miniature biodegradable polymeric matrix contains anti-KRAS G12D siRNA for non-operable Locally Advanced Pancreatic Cancer (LAPC) patients." (PMID 40805153, 2025). "Paradoxically, despite KRAS’s presumed role in pancreatic cancer PM32, our analysis of 1970 pancreatic cases revealed no significantly enriched PM-associated genes, suggesting non-genomic drivers." (PMID 41390696, 2025). "Accordingly, simultaneous inhibition of KRAS, MEK, and JAK2 could be an innovative therapeutic strategy against KRAS‐mutant pancreatic cancer." (PMID 39400496, 2025). "Clinically, CSI is applied as an adjuvant cancer therapy not a single compound, with our findings demonstrating that CSI-derived bufadienolides notably suppress pancreatic cancer cell proliferation by inducing G2/M arrest, potentially via the p-EGFR/KRAS/p-ERK1/2 pathway." (PMID 39770538, 2024). "In the presence of oncogenic KRAS, IL-17 induces transcription of DCLK1 and ALDH1A1 (a marker of embryonic stem cells) through classical pathway activation, and directly upregulates DCLK1 expression in pancreatic cancer cells in a dose-dependent manner." (PMID 39839479, 2024). "Taken together, the preclinical evidence presented here hints at a potential therapeutic synergism of KRAS inhibition by means of AMG510 (Sotorasib) or BI-3406 in combination with MEK inhibition by Binimetinib and concomitant irradiation in KRAS mutant pancreatic cancer." (PMID 38892436, 2024). "Furthermore, mutant KRAS expression can also increase NRF2 transcription, activate the ROS detoxification program, and help pancreatic cancer cells resist ROS." (PMID 39609317, 2024). "Unfortunately, due to the low frequency of KRASG12C mutations in PDAC, there is not enough patient data to understand how pancreatic tumors will adapt to direct targeted KRAS inhibitor therapies." (PMID 38800401, 2024). "Next, we investigated whether K19-SOCS7 could enable the degradation of endogenous KRAS in MIA PaCa-2, a KRASG12C mutant pancreatic cancer cell line." (PMID 38746666, 2024). "Combinatorial approaches targeting multiple KRAS effector pathways, such as MAP kinase and PI3K/AKT, are considered, along with therapies addressing the adaptability of metabolic pathways and the heterogeneity of pancreatic tumors." (PMID 38666907, 2024).
pancreatic cancer (continued). "Furthermore, we show that MTX-531 improves therapeutic outcome in combination with RAS pathway intervention in BRAF-mutant and KRAS-mutant CRC and pancreatic cancer." (PMID 38992135, 2024). "In pancreatic cancer, glutamine deprivation has been shown to reduce GPX4 expression, a central regulator of ferroptosis, thus sensitizing cells to ferroptosis through the KRAS/MAPK-NRF2-GPX4 pathway." (PMID 39518098, 2024). "Among all pathogenic KRAS mutations, the prevalence of G12C was similar between TACSTD2-high versus TACSTD2-low groups in both CRC (7.3% vs 6.4%) and pancreatic cancer (1.5% vs 1.5%; P > .05; data not shown)." (PMID 38986529, 2024). "Finally, we leverage these properties to construct a SOCS7-based KRAS degrader, that reduces RAS-dependent signaling and impedes the proliferation of pancreatic cancer cells." (PMID 38746666, 2024). "Pancreatic cancer cells use the non-canonical KRAS-induced glutamine pathway to maintain redox homeostasis, supporting cell growth by increasing the nicotinamide adenine dinucleotide phosphate (NADPH/NADP +) ratio." (PMID 39609317, 2024). "For instance, APC- or MYC-driven pancreatic tumors were sensitive to depletion of serine and glycine, leading to reduced growth; in contrast, KRAS-driven tumors were not affected by serine and glycine removal." (PMID 38216787, 2024). "Patients with pancreatic tumours with a nonmutated KRAS proto-oncogene have a higher incidence of potentially treatable alterations." (PMID 38329611, 2024). "Importantly, the two new compounds show significantly lower IC50 and higher specificity against the G12D KRAS mutant human pancreatic cancer cell line PANC-1, as compared to the recently described selective G12D KRAS inhibitor MRTX-1133." (PMID 38473821, 2024). "In addition, YAP acts downstream of mutant KRAS, and activation of YAP was found to drive KRAS-independent tumor relapse in preclinical models of pancreatic cancer." (PMID 39046443, 2024). "A phase I clinical trial (NCT03948763) of the KRAS mRNA vaccine V941 (mRNA-5671) in KRAS-mutated NSCLC, pancreatic cancer, and CRC has been completed, but no results have been posted." (PMID 38763973, 2024). "In a study comparing a group of young patients (< 50 years old) with pancreatic cancer with a group with the usual age, the younger group had a higher proportion of the nonmutated KRAS gene than the older group (17% vs. 4%)." (PMID 38329611, 2024). "Together, these results suggest that targeting transcription via dual inhibition of TOP1 and BRD4 can specifically target KRAS- and MYC-driven pancreatic tumors and provide viable and clinically applicable therapy for hard-to-treat cancer entities such as PDAC and panNEC." (PMID 37831776, 2023). "In addition to the reprogramming of glycolysis, mutant KRAS signaling contributes to phosphoglycerate kinase 1 (PGK1) translocation in mitochondrion, leading to PDHK1 phosphorylation and Oxphos restriction in pancreatic cancer cells." (PMID 37187730, 2023). "Cell migration and invasion have been proven to be important roles of CTEN, involving several proteins and signaling pathways, including KRAS/BRAF, Src/ROCK/SNAIL, ILK, and FAK in colorectal and pancreatic cancer, and Rho/ROCK/MLC in hepatocellular carcinoma, via DLC-1." (PMID 36851390, 2023). "To verify RAS-driven degradation and the cause-and-effect link between RAS degradation and drug efficacy, we first observed the degradation of KRAS G12D in SW1990 cells but not KRAS G12C in MIA PaCa-2 human pancreatic cancer cells (homozygous KRAS G12C)." (PMID 37513471, 2023). "ANAPC2 was upregulated by artesunate and degraded the KRAS protein in colon cancer cells, so ANAPC2 may play an important role in pancreatic cancer in a similar manner." (PMID 38304253, 2023).